RUVBL1 (RuvB like AAA ATPase 1)
Diseases named in the same sentence as RUVBL1 in open-access papers (continued):
Sharing a sentence is not in itself a finding about the gene and the disease.
cancer (35 papers, 2012 to 2025). A tumor composed of atypical neoplastic, often pleomorphic cells that invade other tissues. "Taken together, we report for the first time a unique interaction of TaPHB-1 with bovine RUVBL-1 that is likely needed to cause cancer-like hallmarks during theileriosis." (PMID 36651733, 2023). "Targeting RUVBL1/2 causes synthetic lethality in mTORC1-hyperactive cancer cells, providing a selective therapeutic opportunity for tumors with high mTORC1 activation." (PMID 36438486, 2022). "RUVBL1/2 complex has been implicated in many cellular, physiological, as well as pathogenic processes, ranging from energy metabolism, glucose and lipid homeostasis, DNA repair, transcriptions, protein degradation, to cell growth and cancers." (PMID 34276666, 2021). "RUVBL1 and RUVBL2, also known as RUVBL1/2 are essential AAA+ ATPases that function as co-chaperones and are strongly associated with cancer." (PMID 40001953, 2025). "We also present evidence that RUVBL1/2 can function more broadly to support oncogenic TFs important in other cancer contexts." (PMID 41241675, 2025). "Although RUVBL1/2 are essential proteins in all eukaryotic cells, independent laboratories have developed small molecule inhibitors of RUVBL1/2 ATPase activity, which have anti-tumor activity in pre-clinical cancer models at well-tolerated doses." (PMID 41241675, 2025). "The observed therapeutic effects of RUVBL1/2 inhibitors in cancer-bearing mice raise the possibility that this AAA+ ATPase activity regulates oncoprotein function." (PMID 41241675, 2025). "For example, both POU2F3 and SOX10 also bind RUVBL1/2 in an ATPase-dependent manner, and RUVBL1/2 inhibition broadly suppresses lineage-specific gene expression across several cancer types." (PMID 41241675, 2025). "Mechanistically, RUVBL1 was required for MYC to establish oncogenic and immunoevasive gene expression identifying the RUVBL1/2 complex as a druggable vulnerability in MYC-driven cancer." (PMID 38821858, 2024). "Overexpression of RUVBL1, RUVBL2, ILF2, ILF3, and HNRNPM are observed in various cancers with their progression (RUVBL1 and RUVBL222,46, ILF2 and ILF347–49, HNRNPM50,51)." (PMID 38225262, 2024). "RUVBL1 and RUVBL2 (collectively RUVBL1/2) are essential AAA+ ATPases that function as co-chaperones and have been implicated in cancer." (PMID 38609375, 2024). "RUVBL1 and RUVBL2 form a subcomplex of many chromatin remodeling complexes implicated in cancer progression." (PMID 39201707, 2024). "For instance, higher levels of CHD1L, HDAC1, MUTYH, NEIL3, POLR2L, RUVBL1, and SPP1 expression in cancer cells have been linked to higher levels of drug resistance to nelarabine, acridine, chlorambucil, dexrazoxane, cladribine, and other drugs." (PMID 37923899, 2023). "The expression of RUVBL1 is upregulated in many human tumors such as HCC and is associated with more aggressive cancer types." (PMID 36531219, 2022). "In the TCGA cohort analysis, similarly to RUVBL1 protein expression, mRNA levels were significantly up-regulated in tumor tissues compared to non-cancer normal tissues (p < 0.001)." (PMID 36242708, 2022). "Further study demonstrated that RUVBL1/2 proteins are pivotal for the vulnerabilities of mTORC1-addicted cancer cells." (PMID 36438486, 2022). "In mammalian cells, overexpression of the RVB1/2 homologs, RUVBL1/2, is correlated with tumor growth and poor prognosis in several cancer types, yet precise mechanisms for how these proteins impact cancer progression are unclear." (PMID 36107469, 2022). "We performed western blot analyses with different cancer cell lines and found that RUVBL1/2 were highly expressed in MCF-7 and K562 cells and were expressed at relatively lower levels in GM12878, U2OS, and HepG2 cells." (PMID 36171202, 2022). "On the other hand, a selective inhibitor of the RUVBL1/2 complex has been developed recently and showed efficacy as an experimental cancer therapeutics." (PMID 34276666, 2021).
cancer (continued). "They found that Liddean affected the oligomeric state of RUVBL2 and led to a shift of RUVBL1/2 complex localization from the cytoplasm to the nucleus in cancer cells." (PMID 32295120, 2020). "Widely reported as an oncogene in cancer, RUVBL1 is related to prognosis of patients with carcinoma." (PMID 31665067, 2019). "RUVBL1/2 is upregulated in a variety of cancers, including colon and liver and the ATPase activity of RUVBL2 was shown to be required for sustained growth and viability of these tumor cells." (PMID 26201077, 2015). "RUVBL1 is a highly conserved AAA(+) ATPase whose expression as well as expression of its homolog RUVBL2 was high in different cancers." (PMID 23443080, 2012). "In addition, our findings also suggest a broader capacity of RUVBL1/2 to interact with multiple cancer-relevant TFs." (PMID 41241675, 2025). "Thus, a possibility exists that RUVBL1/2 is a therapeutic cancer target because it acts as a rate-limiting enzymatic coactivator required for the aberrant activity of TF oncoproteins such as KLF5." (PMID 41241675, 2025). "In addition to the important identification of RUVBL1 as a candidate for the development of an MYC-based cancer therapy, several further observations emerged from this study." (PMID 38821858, 2024). "Pathogenetic roles of RUVBL1/2 in diseases may include inflammatory response, cancer invasion/metastasis, drug resistance, and radio resistance." (PMID 39201707, 2024). "We speculate that the interaction between PHB-1 and RUVBL-1 will not only have implications in the arena of parasite biology but also shall shed some light on cancer progression." (PMID 36651733, 2023). "Previous studies from other authors have reported that high RUVBL1 expression was significantly associated with the aggressive clinical features of cancer, but we did not observe any significant relationship." (PMID 36242708, 2022). "Besides regulating the cell response to stress conditions, RuvBL1 and RuvBL2 have known implications in cancer." (PMID 30213962, 2018). "Interestingly, two components of all INO80 complexes RuvBL1 (Pontin) and RuvBL2 (Reptin) have been found deregulated in human cancers." (PMID 21924352, 2012). "It is well established that Ruvbl1 plays multiple roles involved in cell development and proliferation and modulating its activity by either depletion or overexpression can lead to several cellular developmental abnormalities such as arrested larval development, cellular death, cancer and others." (PMID 39775671, 2024). "Notably, RUVBL1/2 complex inhibitors are being developed as potential anti-cancer therapeutics." (PMID 34276666, 2021). "RUVBL1 has been reported as an oncogene in various cancers, but its role in OS remains unknown." (PMID 31665067, 2019). "Taken together, these results suggest that RUVBL1/2 cooperates with KLF5 to activate transcriptional programs that define lineage identity in PDAC, and potentially other cancer types." (PMID 41241675, 2025). "Using this assay, we also detected the known interaction between RUVBL1/2 and MYC47, as well as interactions with other cancer-promoting TFs, including POU2F3 and MYB." (PMID 41241675, 2025). "We validated increased RUVBL1 expression in patients with human cancer at the protein level using an in-house tissue microarray (TMA) containing PDAC tumour, benign acinar and benign ductal tissue specimens stained for RUVBL1." (PMID 38821858, 2024). "As building blocks of diverse macromolecular complexes, the AAA+ ATPases RUVBL1 and RUVBL2 are crucial for many cellular activities including cancer-related processes." (PMID 38609375, 2024).
cancer (continued). "RUVBL1 and RUVBL2, referred to as RUVBL1/2, are crucial AAA+ ATPases that act as co-chaperones and are connected to cancer." (PMID 38609375, 2024). "For NVL2, RUVBL1, and DKC1, the amplification frequency >5% occurred in eight, seven, and five cancer types, respectively." (PMID 36239411, 2023). "DKC1, RUVBL1, NHP2, and TERC expression was also inversely correlated with DNA methylation in most cancer types." (PMID 36239411, 2023). "Increased expression of both RUVBL1 and RUVBL2 in various cancer types was reported such as hepatocellular, breast, lung, leukemia, colorectal and lymphatic carcinomas." (PMID 32295120, 2020). "The genes of the DKC1 branch including DKC1, encoding the telomerase subunit dyskerin, and the telomerase complex assembly genes Pontin (RUVBL1) and Reptin (RUVBL2) are consistently up-regulated in all cancer subtypes." (PMID 31750255, 2019). "In cancer cells, expression of the metastasis suppressor KAI1 is regulated by binding of either Tip60:RuvBL1 or β-catenin:RuvBL2SUMO to its promoter." (PMID 30213962, 2018). "We tested the effect of CB6644 (targeting RUVBL1/2 complex), MKT077 (inhibiting HSPA9), selinexor (blocking XPO1, nuclear exportin), and MeAIB (targeting SLC38A2) on cell lines representing three different cancer types versus the normal fibroblasts." (PMID 39217152, 2024). "In agreement with the previous observations by us and others 31, 52, despite being as a Ca2+ sensor, HPCAL1 interacted with RUVBL1 that was clearly not affected by Ca2+ concentration in cancers." (PMID 36438486, 2022). "By controlling C-RAF kinase’s phosphorylation, RUVBL1 influences the RAF/MEK/ERK pathway, which is known to be overactivated in several cancer types, including non-small lung carcinoma (NSCLC), leading to cancer progression." (PMID 36242708, 2022). "While the cytoplasmic location of RUVBL1 may be involved in EMT and cancer metastasis, we found that RUVBL1 is located both in the cytoplasm and nucleus in MG63 and U2OS cells." (PMID 31665067, 2019). "Due to variations between datasets, FABP4 expression did not predict patient disease-free survival in the TCGA Firehose Legacy dataset, while U2AF2, RUVBL1, XPO1, and POSTN did not predict disease-free survival in the BS Taylor, Cancer Cell, 2010 dataset." (PMID 39402324, 2024). "This mandates a search for targetable signatures, such as RUVBL1, HSPA9, and XPO1, whose redundancy is limited by directly non-overlapping roles in cancer cell metabolism." (PMID 39217152, 2024). "Using RNAi screening of the commonly activated molecular programs, we found a signature of three proteins - RUVBL1, HSPA9, and XPO1, which could be efficiently targeted by novel drug combinations in the studied cancer types." (PMID 39217152, 2024).
tumor (30 papers, 2012 to 2025). "GO analysis revealed that the knockdown of Lyn/RUVBL1 resulted in significant enrichment in cell adhesion, a process closely associated with tumor metastasis." (PMID 39665272, 2025). "Several studies have demonstrated that pharmacological targeting of RUVBL1/2 can extend the survival of tumor-bearing mice, although the mechanisms that underlie a tumor-specific dependence on RUVBL1/2 ATPase activity are unclear." (PMID 41241675, 2025). "We concluded that high MYC expression causes tumour cells to depend on the complete RUVBL1 protein function." (PMID 38821858, 2024). "Suppression of RUVBL1 leads to attenuated tumor growth, loss of histone H4 acetylation, and ablated MYC signaling." (PMID 37075745, 2023). "Further exploration through loss-of-function assays in our study unmasked the anti-tumor property of RUVBL1 depletion via siRNA as evidenced by suppressed proliferation, migration and invasion of UVM cells as well as promoted cell apoptosis while blocking cell cycle." (PMID 37076452, 2023). "Consistent with the observation that Hpcal1 deficiency resulted in dramatical increase of tumor growth above, this effect was partially reversed in tumors with simultaneous deficiency of Hpcal1 and Ruvbl1, considering that the tumor number was higher compared with that of Ruvbl1-deleted tumors." (PMID 36438486, 2022). "In conclusion, our study underscores the potential of CB-6644, a selective inhibitor of the RUVBL1/2 complex, as a promising anti-tumor agent in MM." (PMID 39201707, 2024). "Subsequently, we conducted immunohistochemical staining to examine the expression of the RUVBL1 protein within our cohort, focusing on tissue samples from ccRCC and adjacent non-tumor tissues." (PMID 38610951, 2024). "In support of this proposition, four of 11 mice with orthotopic tumours were cured by a combinatorial treatment consisting of transient RUVBL1 depletion and PD-1 checkpoint blockade." (PMID 38821858, 2024). "Again, in tumours excised when mice reached the endpoint, TIR1F74G expression was drastically reduced in all auxin-treated animals, suggesting that even advanced tumours strictly depend on RUVBL1." (PMID 38821858, 2024). "We concluded that patients with PDAC with elevated MYC expression also overexpress RUVBL1, and that tumours with the highest expression of both proteins are the most aggressive." (PMID 38821858, 2024). "We found it intriguing that RUVBL1 depletion triggered strong tumour regression in vivo, whereas the same tumour cells only arrested in culture." (PMID 38821858, 2024). "Immunohistochemistry confirmed the auxin-mediated depletion of RUVBL1 in tumour cells, while RUVBL1 levels in the surrounding healthy tissue and stromal cells were not affected." (PMID 38821858, 2024). "We noted that the frequency of high RUVBL1 mRNA expression increased with tumor grades (p = 0.0337), pT status (p = 0.0009), and TNM stage (p = 0.0005)." (PMID 38610951, 2024). "We examined the transcriptional levels of key tumor-dependent genes (RUVBL1, GTF3C4, TIGD1, and TAF1A) between groups categorized by MYCN expression levels (low vs. high, n = 30 each) using Q-RT-PCR." (PMID 39175876, 2024). "Among these differential proteins related to DNA repair, we found that RUVBL1 was consistently high expression level in different tumor tissues treated with radiation." (PMID 38609375, 2024). "GART also enhances the stability of RuvB‐like AAA ATPase 1 (RUVBL1) through methylating its K7 site, which consequently aberrantly activates the Wnt/β‐catenin signaling pathway to induce tumor stemness." (PMID 37439412, 2023). "Collectively, our findings on the tumor-supporting action of RUVBL1 provide new insights into the mechanism of UVM and offer potential targets for chromatin remodeling." (PMID 37076452, 2023). "Remarkably, the combination of sgRUVBL1 and JQ1 dramatically inhibited the in vivo EwS tumor progression (red), providing a proof‐of‐concept efficacy of synergistic targeting RUVBL1 and MYC in EwS." (PMID 37075745, 2023).
tumor (continued). "Using a series of epigenetics‐ and complex‐focused CRISPR screens, RUVBL1, the ATPase component of NuA4 histone acetyltransferase complex, is identified to be essential for EwS tumor progression." (PMID 37075745, 2023). "This investigation revealed that RUVBL1 was closely associated with CRC development, and the expression levels of RUVBL1 in the tumor and adjacent samples were increased compared with healthy samples in the GSE44076 database." (PMID 37439412, 2023). "Many specific RUVBL1-involved signaling pathways have come to light, which means that RUVBL1 has been confirmed as a tumor therapeutic target." (PMID 36052378, 2022). "In conclusion, we finally identified five genes most associated with tumor progression and prognosis: VRK1, NUP37, HMMR, SPC25, and RUVBL1." (PMID 36052378, 2022). "However, some were also essential for tumours in their natural environment and, among these, the ATPases RUVBL1 and RUVBL2 ranked first." (PMID 38821858, 2024). "Finally, we observed that tumour regression after RUVBL1 depletion was accompanied by a massive infiltration of CD3-positive immune cells in the KPC model used here." (PMID 38821858, 2024). "The results showed that overexpression of RUVBL1 significantly increased tumor growth and weight." (PMID 38609375, 2024). "Interestingly, RUVBL1 expression is higher in basal and undifferentiated tumours than in glandular and differentiated tumours, respectively." (PMID 38821858, 2024). "We then examined RUVBL1 levels in tumours over time after a single auxin injection." (PMID 38821858, 2024). "This is necessary because human PDAC tumours are characterised by a high degree of phenotypic and genetic heterogeneity and may therefore show variable dependence on RUVBL1." (PMID 38821858, 2024). "The contribution of RUVBL1 to tumor progression has been reported to rely on chromatin remodeling." (PMID 37076452, 2023). "More generally, knockdown of RuvBL1-RuvBL2 promotes genome instability and, therefore, RuvBL1-RuvBL2 may act as a tumour suppressor." (PMID 25428364, 2014). "Furthermore, this mechanism raises the possibility that inhibition of RUVBL1/2 could be a strategy to reprogram tumor cell identity into an alternative cell state that is more amenable to treatment with other therapies." (PMID 41241675, 2025). "However, the mechanism of how RUVBL1/2 regulates tumor radiation resistance is still unclear." (PMID 38609375, 2024). "The analysis results of biological process identified RUVBL1 to be mainly involved in the biological processes related to chromatin remodeling, such as histone modification, DNA repair regulation, DNA reorganization, DNA conformational change and double-stranded unfolding, in tumor cells." (PMID 37076452, 2023). "Pharmacologic inhibition of RUVBL1/2 ATPase activity disrupts this interaction, impairs KLF5 function, and suppresses tumor cell proliferation." (PMID 41241675, 2025). "The expression of RUVBL1 and HIF-1α proteins in our cohort was assessed using immunohistochemistry in ccRCC tissue samples and adjacent non-tumor tissues." (PMID 38610951, 2024). "WB analysis confirmed that the levels of both the GART and RUVBL1 proteins were elevated in both GART‐OE CRC cell lines and the AOM/DSS‐induced tumor tissues." (PMID 37439412, 2023). "We found that RUVBL1 and HNRNPU proteins and mRNA levels were higher in tumor tissues as compared to adjacent/normal tissues." (PMID 36242708, 2022). "In this dataset, all the 7-gene candidates exhibited a significant increase of mRNA expression in the metastasis group relative to localised tumours, with RUVBL1 exhibiting near statistical significance (U2AF2 P = 0.0106, RUVBL1 P = 0.051, HDGF P < 0.0001, FABP4 P = 0.0005, and STMN1 P = 0.032)." (PMID 39402324, 2024). "RUVBL1 is a highly conserved AAA+ ATPase in eukaryotic cells and participates in tumor progression." (PMID 36052378, 2022).
tumor (continued). "Moreover, RUVBL1 was frequently shown to be a coactivator for transcriptions of various genes including KAI1, a tumor suppressor gene which inhibits tumor metastasis." (PMID 31665067, 2019). "Degradation of RUVBL1 by the auxin-degron system led to the arrest of cultured PDAC cells but not untransformed cells and to complete tumour regression in mice, which was preceded by immune cell infiltration." (PMID 38821858, 2024).